CRP (C-reactive protein)
Diseases named in the same sentence as CRP in open-access papers (continued):
Sharing a sentence is not in itself a finding about the gene and the disease.
Obesity (continued). "After adjustments, overweight/obesity was associated with age, family history of overweight/obesity, total daily insulin dose, hypertension, adherence to diet, type of health care insurance, use of metformin, levels of C-reactive protein, triglycerides, uric acid and HDL-cholesterol." (PMID 36823646, 2023). "Elevated concentrations of markers and mediators of inflammation and acute-phase reactants, including C-reactive protein, interleukin (IL)-6, and plasminogen activator inhibitor-1, confirmed the epidemiologic associations between inflammation and obesity and type II diabetes." (PMID 37298118, 2023). "On bivariate analysis, a higher risk of HAI was associated with male sex, obesity, lower lymphocyte count, CRP > 10 mg/dL, ferritin > 500 mg/dL, LDH > 246 IU/L, D-dimer > 500 mg/mL, use of IMV on the first 24 h upon admission, and treatment with corticosteroids and tocilizumab." (PMID 37508204, 2023). "We identified an increased risk of hepatic dysfunction by biogenic amine ingestion in obesity and confirmed that both blood and liver biomarkers, including CRP, MAO, IL-1β, and PARP-1, are helpful markers for evaluating hepatic function in biogenic amine-induced liver damage in obesity." (PMID 36899958, 2023). "Furthermore, obesity during pregnancy is associated with increased levels of C-reactive protein (CRP), interleukin (IL)-6, tumor-necrosis factor-α (TNFα) and leptin." (PMID 37731394, 2023). "Obesity is associated with a chronic state of low-grade inflammation, characterized by elevated levels of pro-inflammatory markers such as C-reactive protein (CRP), interleukin-6 (IL-6), and tumor necrosis factor-alpha (TNF-α)." (PMID 37623340, 2023). "C-reactive protein (CRP) is a major factor that has been associated with obesity." (PMID 37237937, 2023). "Considering the measured blood parameters, patients showed typical obesity-associated signs of a low-grade chronic inflammation characterized by significantly elevated levels of both circulating C-reactive protein (CRP) (median= 7.7 mg/L) and circulating fibrinogen (median = 3.7 g/L)." (PMID 37266430, 2023). "As with other markers of inflammation, obesity is associated with higher levels of CRP." (PMID 37490455, 2023). "Besides genetic factors, obesity is another well‐established risk factor for chronic inflammation, with higher serum CRP concentrations being a marker of elevated adiposity." (PMID 37493001, 2023). "Our results found that dyslipidemic women consuming the LP + HA pattern were correlated with less anemia but higher cholesterol levels, whereas those consuming the HP + LA pattern were associated with more anemia but less obesity and lower cholesterol and CRP levels." (PMID 35627766, 2022). "The studies showed benefits associated with IBR (e.g., cytokines, adipokines, and C-reactive protein) in various clinical conditions, including healthy populations and some chronic diseases (such as obesity, aging disorders, and knee osteoarthritis), using several WBV protocols." (PMID 36429572, 2022). "In line with this hypothesis, Stenholm and colleagues suggested a mediating role of CRP on the association between obesity and walking limitations (a measure of poor PF)." (PMID 35301057, 2022). "In linear regression, UA was associated with obesity, C-reactive protein, and renal function." (PMID 35885024, 2022). "Obesity predisposes the body to a pro-inflammatory state by adipose tissue releasing inflammatory mediators, such as interleukin 6, which triggers hepatocytes to synthesize and secrete CRP." (PMID 36235852, 2022). "Apart from the consensus classification of the metabolic and obesity phenotypes utilised in this study, others have found strong association of systemic inflammation (measured by hs-CRP) and insulin resistance (HOMA-IR) in the development of metabolic syndrome." (PMID 35267891, 2022).
Obesity (continued). "This high consumption of traditional diet may contribute to the lower prevalence of obesity, and thus reducing abdominal visceral fat as a cause for the elevation of CRP levels." (PMID 34478414, 2022). "CRP levels are associated with several obesity complications in children." (PMID 36038871, 2022). "However, numerous studies have reported that CRP was consistently associated with obesity and depression." (PMID 36387880, 2022). "In addition, we determined the levels of CRP to evaluate the severity of the inflammatory state caused by obesity." (PMID 36612926, 2022). "A high DII score, which was associated with elevated inflammatory markers, such as C-reactive protein (CRP), indicates a pro-inflammation diet and has been reported to be correlated with an increased risk of obesity, type 2 diabetes, and cardiovascular diseases." (PMID 35807737, 2022). "Elevated serum CRP is associated with obesity among children." (PMID 35379317, 2022). "We investigated whether and the extent to which C-reactive protein (CRP) mediates the association between early-adult obesity and mid-life PF." (PMID 35301057, 2022). "Associations between CRP, leptin and leptin-to-adiponectin ratio with breast cancer risk may represent the dual effect of obesity by menopausal status although this deserves further investigation." (PMID 35430795, 2022). "Due to elevated CRP levels in overweight and obese adults, we also wanted to know whether there exist causal associations between thyroid signaling and obesity traits." (PMID 35996695, 2022). "Nervonic acid was also reduced along with a reduction in body weight in obese women and may have protective effects in obesity-related metabolic risk factors such as lipid levels, fasting blood glucose, CRP and leptin." (PMID 36140306, 2022). "Additionally, anthocyanins can reduce pro-inflammatory markers associated with obesity, such as CRP, IL-6, and TNF-α." (PMID 35740977, 2022). "Elevated CRP, for instance, has long been considered as a risk indicator of cardiovascular disease, and increase in CRP level is also observed in a number of metabolic disorders, including obesity." (PMID 36235787, 2022). "Furthermore, numerous human and animal studies demonstrated the associations of elevated serum CRP levels with obesity and the progression of IR leading to T2DM." (PMID 35620114, 2022). "Both gender and increasing obesity were associated with increased levels of CRP." (PMID 35035976, 2022). "Additionally, none of the patients’ demographics, BMI nutrition status (overweight, obesity), diagnostic category, the severity of illness, temperature, heart rate, blood gases, or CRP was independently associated with the REEVCO2–REEIC difference." (PMID 36235863, 2022). "Several reports consider CRP to be a consequence of an obesity condition rather than the cause; conversely, increasing evidence establishes a causal role of CRP elevation in the onset and development of obesity by causing extensive tuning in the innate immune system and energy expenditure system." (PMID 35456438, 2022). "Thus, CRP plays an important role in the prevention of chronic inflammation associated with obesity in the early stages of life." (PMID 35379317, 2022). "Those overweight or with obesity may have a protective effect on recurrent stroke events among patients with stroke; it can partly explain the low relative risk of stroke in individuals with elevated-CRP levels, hypertension, and obesity." (PMID 36262245, 2022). "A study in Japan reported that CRP increased the risk of obesity in school children." (PMID 35379317, 2022). "CRP is produced in the liver as an acute phase protein in response to the release of IL-6 by macrophages or adipocytes, and the serum level of IL-6 is associated with long-term health risks in women with obesity and type-2 diabetes mellitus." (PMID 36551953, 2022).
Obesity (continued). "Higher fasting insulin and c-reactive protein are associated with higher body mass index (BMI) and all-cause mortality, so may confound the association between obesity and mortality." (PMID 36030344, 2022). "Finally, the associations between CRP and education weakened after adjusting for obesity-related measures." (PMID 35428237, 2022). "Furthermore, the expression of CXCL11 was associated with C-reactive protein, causing the subfamily to be a potential biomarker for the onset of adipose tissue inflammation in obesity." (PMID 35386146, 2022). "In addition, though an increasing BMI was associated with higher CRP levels in each race and gender, the increase in CRP levels with obesity was greater for women than men (p < 0.001)." (PMID 36304737, 2022). "In the results of this consensus, the measurement of C-reactive protein and ferritin levels is also recommended when evaluating patients with obesity and assessing whether they have other cardiovascular risk factors." (PMID 35887894, 2022). "However, null or weaker mediation effects of the TyG index and CRP were found to associate general obesity with the risk of CRC incidence." (PMID 36407320, 2022). "After further adjustment for socio-demographic characteristics, chronic illnesses, and CRP, these associations were slightly weaker but remained statistically significant at conventional levels (obesity class I: 1.32; 95 %, 1.10 to 1.57: obesity class II-III:1.70; 95 %,1.34 to 2.14)." (PMID 35853559, 2022). "Interestingly, we showed that healthy children with higher baseline levels of high-sensitivity C-Reactive Protein (hs-CRP) were at higher risk of developing overweight/obesity during growth." (PMID 36235787, 2022). "Moreover, studies have documented that higher CRP levels are associated with higher body mass index (BMI) and/or other obesity markers (e.g., body circumferences)." (PMID 35629167, 2022). "With the aim of furthering understanding about potential metabolic links between obesity and foot pain, this cross-sectional study aims to assess whether CRP, TNF-α, and IL-6 are associated with prevalent foot pain and structural foot disorders." (PMID 35941593, 2022). "The association between obesity and maternal CRP level has been observed in pregnant women." (PMID 35768766, 2022). "Our subgroup analysis clearly indicated, however, that increased [Ca2+]ex-induced, CaSR mediated IL-1ß release was not limited to people with a clinically detectable inflammatory state, but was also associated with obesity in individuals with normal CRP levels." (PMID 35931812, 2022). "Weight loss has been shown to improve inflammation in terms of several inflammatory markers associated with obesity, specifically decreases in pro-inflammatory biomarkers (CRP, TNF-α, IL-6, and leptin) and increases in the anti-inflammatory biomarker adiponectin." (PMID 35276970, 2022). "Specifically, we investigated the association between obesity in early-adulthood and PF in mid-life, and whether associations were mediated by CRP." (PMID 35301057, 2022). "Finally, the impact of obesity (in terms of WC) under different CRP risk levels was estimated for the association between dental plaque and PD, that is, between the extent of supragingival biofilm and the periodontal measure." (PMID 32827080, 2021). "In a Japanese prospective study (n = 1,074), the association between CRP and IR was less evident among adults with normal BMI (β 0.93 95% CI 0.86; 1,00) than among those with overweight (β 1.28 95% CI 1.17; 1,41) or obesity (β 2.13 95% CI 1.98; 2.29) (p-valuefor interaction < 0.001)." (PMID 34033278, 2021). "Thus, as obesity and elevated CRP levels are associated with multiple chronic diseases, it is believed that inflammatory markers play a mediating role in their etiology." (PMID 32827080, 2021).
Obesity (continued). "While high levels of CRP are related to an acute inflammatory response, mildly increased circulating CRP is, among others, associated with genetic factors or subclinical inflammatory processes occurring in the context of obesity and other conditions." (PMID 34975902, 2021). "Notably in our study, patients with T2D and high CRP levels were associated with class I obesity and poor glucose control as denoted by a body mass index > 30 kg/m2and elevated FPG levels, respectively." (PMID 35844722, 2021). "The purpose of the present observational prospective study was therefore to elucidate the relationships between pre-surgery high sensitivity-CRP (hs-CRP) values and post-surgery weight loss and liver steatosis and fibrosis in patients with severe obesity undergoing to a Roux-en-Y gastric bypass." (PMID 33919641, 2021). "Both obesity and PD were associated with systemic CRP and fibrinogen concentrations." (PMID 32827080, 2021). "Moreover, obesity causes inflammation and lipid peroxidation by abnormal production of pro-inflammatory factors such as IL-6 and CRP as well as the release of free fatty acids from adipose tissue." (PMID 33596883, 2021). "Severe obesity causes inflammation in visceral adipose tissue; further, it increases CRP levels." (PMID 34262126, 2021). "Obesity is an inflammatory state, and is associated with elevated CRP levels." (PMID 34341450, 2021). "Previous studies have shown that different inflammation biomarkers, such as CRP, TNFα and IL-6, were differently associated with body composition and these may further differ by obesity level and sex." (PMID 33557067, 2021). "In addition to its role in obesity, systemic inflammation, measured by high-sensitivity C-reactive protein (hs-CRP), was associated with MetS in the NHANES Survey." (PMID 34065158, 2021). "Even though clinical studies linked salivary CRP positively as a marker for metabolic syndrome, detection of obesity in children, or pneumonia in neonates, a study published in 2019 with 37 healthy young males showed no clear correlation between salivary and serum concentrations of CRP." (PMID 33673378, 2021). "Furthermore, obesity associated gut inflammation is a possible source for increased plasma levels of CRP, calprotectin, and α-1-antichymotrypsin in obese individuals." (PMID 34066026, 2021). "In conclusion, chronic low-grade inflammation; CRP, myeloid leukocyte populations, specifically classical monocytes and neutrophils associated with obesity in children and adolescents and can cause metabolic dysfunction and cardiovascular disease even in childhood." (PMID 32528415, 2020). "Consistent with our results that obesity was associated with elevated serum levels of CRP and IL-6 independently of OSAS severity and sex, several studies have also reported increases in both CRP and IL-6 levels in overweight and obese patients regardless of sex." (PMID 32629899, 2020). "In particular, obesity has been linked to high CRP levels and changes in the leukocyte profile." (PMID 32210070, 2020). "Thus, a strong positive association has been found between measures of obesity, such as waist circumference (WC) and body mass index (BMI), and CRP levels." (PMID 33182500, 2020). "Obesity as a risk factor for tooth loss may be modified by systemic markers of inflammation such as CRP and IL-6, especially in men." (PMID 32486269, 2020). "Additionally, elevated high-sensitivity C-reactive protein (hs-CRP), as an indicator of low-grade inflammation, has been considered a possible risk factor for cardiovascular diseases associated with obesity and visceral adiposity." (PMID 33182500, 2020). "Moreover, our findings support previous studies which demonstrated that obesity and the metabolic disorders’ risk in children and adolescents are associated with low-grade inflammation, especially on CRP." (PMID 32443557, 2020).
Obesity (continued). "Furthermore, patients with increased levels of CRP, an inflammatory marker related to obesity as well as periodontal inflammation, were at higher risk of losing teeth compared to subjects with lower values of CRP." (PMID 32486269, 2020). "Also, in a study of adolescents, CRP levels were significantly associated with overweight and obesity in both boys and girls." (PMID 32292493, 2020). "Moreover, those with both obesity indices had the highest risk of elevated hs-CRP levels in Korean men and women compared to either individual index of obesity." (PMID 33182500, 2020). "As both IL-6 and CRP are biomarkers of obesity-associated inflammation, this raises the possibility that obesity may impair immunotherapeutic efficacy in patients with breast cancer." (PMID 33123173, 2020). "Additionally, lipid profiles (e.g., total cholesterol, and LDL-C), C-reactive protein, obesity-related cardiovascular risk factors have been found to reduce with ginger intake." (PMID 31935866, 2020). "As shown in the full models that contain obesity, inflammatory biomarkers, and metabolic risk factors (Models 6 and 9), there is a positive association between high sex-specific serum uric acid levels and CRP with T2DM, for both Whites and Blacks." (PMID 32879892, 2020). "Other factors may mediate between obesity and PF, e.g. obesity causally influences inflammation as indicated by biomarkers such as C-reactive protein, which in turn has been postulated to lead to muscle weakness and sarcopenia." (PMID 32142119, 2020). "Here we show that chronic elevation of human CRP at baseline level causes the obesity." (PMID 32154244, 2020). "C-reactive protein (CRP) is a measure of chronic inflammation predictive of cardiovascular disease, and high body mass index (BMI), a ratio of weight to height, indicates overweight or obesity and is associated with an increased risk of many chronic diseases." (PMID 33141863, 2020). "However, with respect to the association between hs-CRP levels and obesity, prior studies have shown that the relationship differs according to various factors, such as age, sex, and ethnicity." (PMID 33182500, 2020). "In conclusion, higher CRF levels may attenuate the detrimental association between obesity and C-reactive protein independently of metabolic phenotype." (PMID 32443557, 2020). "Obesity and in particular central adiposity – the excess deposition of visceral fat – is associated with increased serum levels of pro-inflammatory cytokines such as interleukin 6 (IL-6), C-reactive protein (CRP), and tumor necrosis factor (TNF)." (PMID 32508807, 2020). "The interaction among obstructive sleep apnea syndrome (OSAS) severity, sex, and obesity on cardiovascular risk as determined by serum levels of C-reactive protein (CRP), interleukin-6 (IL-6), and tumor necrosis factor-α (TNF-α) remains unclear." (PMID 32629899, 2020). "In this study, we tested the hypothesis of a positive association between plasma ANGPTL5, and obesity, high sensitivity C-reactive protein (HsCRP) and oxidized low-density lipoprotein (Ox-LDL) in adolescents." (PMID 32286392, 2020). "Obesity and its cardiovascular sequelae have been repeatedly associated with increased CRP." (PMID 29764522, 2019). "Moreover, our present study showed an association between ADMA and CRP in patients with obesity, confirming previously published data in varying sets of patients." (PMID 31234586, 2019). "Both obesity and hypertension interacted with the associations between CRP and incident T2DM." (PMID 30872696, 2019). "Overweight and obesity are clearly associated with alterations in the lipid profile and raise in the markers of systemic inflammation, including C-reactive protein (CRP) and proinflammatory cytokines, such as interleukin- (IL-) 1 beta (IL-1β), IL-6, and tumor necrosis factor alpha (TNF-α)." (PMID 31482005, 2019).